CFHR2 (complement factor H related 2)
Description:
Involved in complement regulation. The dimerized forms have avidity for tissue-bound complement fragments and efficiently compete with the physiological complement inhibitor CFH. Can associate with lipoproteins and may play a role in lipid metabolism.
Synonyms: CFHL2; FHR2; HFL3
Tractability: Antibody: its Gene Ontology location is reachable by antibodies, with high confidence; UniProt places it where antibodies can reach, with medium confidence; UniProt predicts a signal peptide or a membrane-spanning region. PROTAC: its protein half-life has been measured.
Gene: Protein-coding gene on chromosome 1 (196,943,731 to 196,964,115, forward strand). Ensembl gene ENSG00000080910.
Subcellular location: Secreted
Pathways (Reactome):
Immune System: Regulation of Complement cascade
Gene Ontology:
Molecular function: identical protein binding; protein binding; complement component C3b binding
Biological process: positive regulation of complement activation; complement activation
Cellular component: protein-containing complex; extracellular region
Genetic constraint (gnomAD): Loss-of-function variants: 22 observed, 20.96 expected, observed/expected ratio (o/e) 1.05, 90% interval 0.75 to 1.5. The upper end of that interval is the gene's LOEUF score, 1.5, which puts it in group 6 of 6, group 1 being the genes least tolerant of losing a copy. Missense variants: 254 observed, 253.88 expected, observed/expected ratio (o/e) 1, 90% interval 0.9 to 1.11. Synonymous variants: 81 observed, 87.28 expected, observed/expected ratio (o/e) 0.93, 90% interval 0.77 to 1.12.
Homologues: Orthologues: mouse Cfhr1 (63% identical), rat Cfhr1 (62% identical). Paralogues in human: CFHR1 (87% identical), CFHR5 (69% identical), CFH (55% identical), CFHR3 (47% identical), CFHR4 (39% identical), F13B (29% identical), PAPPA (22% identical), PAPPA2 (21% identical), CSMD3 (20% identical), CSMD1 (19% identical), SRPX (18% identical), SVEP1 (18% identical), and 27 more.
Diseases named in the same sentence as CFHR2 in open-access papers:
CFHR2 is named in the same sentence as 18 diseases in open-access papers, as found by Europe PMC text mining. Sharing a sentence is not in itself a finding about the gene and the disease. The quoted sentences say what the papers report.
breast carcinoma (1 paper, 2025). "As a crucial player in terminating growth factor signaling, EPS15 plays an important role in many malignancies, including breast cancer.18) CFHR2 is involved in regulation of the complement cascade and is responsible for the immune response and inflammatory control." (PMID 40678018, 2025).
diabetic kidney disease (1 paper, 2022). Progressive kidney disorder caused by vascular damage to the glomerular capillaries, in patients with diabetes mellitus. "Another study revealed that a higher urine CFHR2 level was associated with a greater risk of death in patients with proteinuric diabetic kidney disease." (PMID 35740418, 2022).
end-stage renal disease (1 paper, 2020). "Patient one who had CFHR2 mutation progressed to end-stage renal disease during follow-up." (PMID 33614676, 2020).
hearing loss (1 paper, 2024). "CFHR2 levels were higher in perilymph obtained from patients with severe to profound hearing loss than in perilymph samples from patients with normal hearing or mild hearing loss." (PMID 38898156, 2024). "Our finding of CFHR2 upregulation and higher activation score for leukocyte migration in PL suggests that an adaptive immune response could be a mechanism contributing to hearing loss." (PMID 38898156, 2024). "Therefore, the high activity of CFHR2 in PL in VS patients with severe to profound hearing loss could be related to altered barrier integrity, allowing more macromolecules and cell migration over the blood-perilymph barrier." (PMID 38898156, 2024).
Listeria infection (1 paper, 2021). "Eight of these genes were similarly inhibited by Listeria infection in PMH: they encode (i) the activating enzyme C1S of the C1 complex, (ii) the central component C3, (iii) the membrane-attack proteins C6 and C8A, and (iv) four complement regulators (C1QTNF6, CFH, CFHR2, VTN)." (PMID 34858876, 2021).
lupus (1 paper, 2020). "Three patients with LN combined with renal TMA have mutation in CFI and CFHR2 genes responsible for complement regulation; this is consistent with previous findings in adult lupus patients." (PMID 33614676, 2020).
Vestibular schwannoma (1 paper, 2024). A vestibular schwannoma (also known as acoustic neuroma, acoustic neurinoma, or acoustic neurilemoma) is a benign, usually slow-growing tumor that develops from the VIIIth cranial nerve supplying the inner ear. "Upregulation of CFHR2 and activation of these pathways indicate chronic inflammation in the cochlea of vestibular schwannoma patients with severe to profound hearing loss compared with patients with normal hearing or mild hearing loss." (PMID 38898156, 2024).
tumor (4 papers, 2013 to 2025). "This is in agreement with our own results, where upregulation of C1QA, C1QC, and CFHR2 in newly diagnosed PCa patients is suggestive of the involvement of tumour inflammatory microenvironment, which may act as a mediator of tumour progression and angiogenesis." (PMID 36831393, 2023). "However, some proteins we found differed from previously identified proteins (Such as ANXA4, CFHR2, CHP, CTSB and so on), which may result from ethnic differences or tumor heterogeneity." (PMID 24139065, 2013).
cancer (2 papers, 2014 to 2023). A tumor composed of atypical neoplastic, often pleomorphic cells that invade other tissues. "The significantly overexpressed sEV proteins in the BC plasma-derived UCT isolates were ALB, COL1A1, CSN1S1, EEF1A2, and RPL3; and the C1S, C5, C7, and CFHR2 sEV proteins in the UCT isolates were the most downregulated proteins in the BC plasma compared to the non-cancer control." (PMID 37895140, 2023).
infection (2 papers, 2010 to 2012). The state of being infected such as from the introduction of a foreign agent such as serum, vaccine, antigenic substance or organism. "Taken together, we identified complement proteins CFHR2 and CFHR5 as novel ligands for the infection-associated CRASP-4/ErpC protein of B. burgdorferi." (PMID 22400034, 2012). "In this study, we extend the characterization of molecular interaction of CFH/CFHR proteins and show that the infection-associated CRASP-4/ErpC protein of B. burgdorferi binds the host complement regulators CFHR1, CFHR2, and CFHR5, and to some extent CFH." (PMID 22400034, 2012). "Here, we extend the characterization of the infection-associated CRASP proteins, CRASP-3 and CRASP-5 of B. burgdorferi s.s. and show that these two molecules bind the host immune regulators CFHR2 and CFHR5." (PMID 20975954, 2010). "In summary, we identified two new ligands, CFHR2 and CFHR5 for the infection-associated CRASP-3 and CRASP-5 proteins of B. burgdorferi." (PMID 20975954, 2010).
renal diseases (1 paper, 2015). "Importantly, three recent reports showed that CFHR1, CFHR2, and CFHR5 deregulate complement by competing with FH for binding to C3b, and thus they may rather enhance complement activation in human renal diseases." (PMID 25855355, 2015).
CFHR2 also shares sentences with these, for which no sentence is quoted: atherosclerosis (1 paper); cardiovascular disease (1); complement 3 glomerulopathy (1); COVID-19 (1); diabetes (1); hemolytic-uremic syndrome (1); Insulin resistance (1).